MIR764 (microRNA 764)
Synonyms: hsa-mir-764
Gene: MicroRNA gene on chromosome X (114,639,435 to 114,639,519, forward strand). Ensembl gene ENSG00000212100.
Gene Ontology:
Biological process: miRNA-mediated post-transcriptional gene silencing
Cellular component: RISC complex